STAT1 (signal transducer and activator of transcription 1)
Diseases named in the same sentence as STAT1 in open-access papers (continued):
Sharing a sentence is not in itself a finding about the gene and the disease.
Arthritis (continued). "Moreover, analysis of CD4+ T cells from inguinal draining lymph nodes of gp130Y757F:Y757F mice with arthritis showed that genetic ablation of Stat1 in these animals enhanced the expression of several STAT3 regulated cytokines involved in T cell‐driven synovitis." (PMID 34618359, 2022). "Similarly, poly(lactic-co-glycolytic) acid (PLGA) nanoparticles coated with arginine-glycine-aspartate (RGD) peptide and encapsulating STAT1-targeting siRNAs were effective in suppressing arthritis via selective inhibition of macrophage and dendritic cell activation." (PMID 25561237, 2014). "Reference mapping showed that the majority of ICI-arthritis myeloid cells mapped onto four RA myeloid clusters: IL1B + FCN1 + HBEGF+, STAT1+ CXCL10+, SPP1+, and MERTK+ HBEGF+ clusters." (PMID 40662950, 2025). "These targets modulate the IL-6/STAT1/STAT3 pathway, which has been shown to significantly prevent and treat gout and arthritis." (PMID 40170729, 2025). "In an adjuvant-induced arthritis model of RA, CCR2, and the expression of other chemokines were increased, accompanied by increased activation of JAK/STAT1/STAT3 pathways, as well as macrophage and endothelial cell infiltration." (PMID 37457301, 2023). "These parameters most likely reflect concerns based on the published experience with JAKinibs in other scenarios, such as myelofibrosis, arthritis, and graft-versus-host disease (GVHD), as well as STAT1 GOF cases, FDA and EMA recommendations." (PMID 35486339, 2022). "Pkm2 intervention reduced the severity of PIA, including macroscopic arthritis scores, perimeter changes of midpaw, synovitis, and bone and cartilage destruction, and reduced ST in rat ED1 and p-Stat1-positive cell populations." (PMID 34899740, 2021). "Inhibition of PKM2 reduces phosphorylation levels of STAT1 and STAT3 and inhibits the transcription of downstream genes regulating pro-inflammatory cytokines, thereby alleviating experimental arthritis." (PMID 34899740, 2021). "The role of the transcription factor for the inhibition of inflammation has been shown in STAT-1-/- mice with exacerbated ZIA and in mice with established arthritis treated with nanoparticles encapsulating STAT1-targeted siRNAs." (PMID 22830570, 2012). "In the AIA model, administration of the STAT-1 decoy ODN reduced typical symptoms such as joint swelling, the DTH reaction and histopathological signs of arthritis." (PMID 16507120, 2006). "The observed decrease in the arthritis score and in the disease symptoms were comparable in the anti-CD40L and STAT-1 decoy ODN arm of the study." (PMID 16507120, 2006). "However, in other mouse models, the IFN-γ/STAT1 pathway has increased and the IL-4/STAT6 pathway decreased the severity of arthritis." (PMID 27942004, 2016).
HCMV infection (17 papers, 2014 to 2024). "Future studies will investigate these possibilities to define the mechanisms by which UL138-complexes sustain STAT1 activity during HCMV infection." (PMID 37289831, 2023). "The level of the STAT1 gene has been shown to increase in CD34+HPC cells of B7-H4-/- mice with human cytomegalovirus infection." (PMID 36514159, 2022). "In human monocytes, IFN-independent, biphasic activation of STAT1 with differential phosphorylation at early (30 min) compared to late (24 h) time points post-HCMV infection appears to influence motility, migration, differentiation and polarization." (PMID 31921100, 2019). "STAT1 and STAT2 were also associated with cytomegalovirus infection, in this case, likely through the activation of signaling pathways driven by the autocrine/paracrine secretion of type-I and type-II interferons induced by IRF and NF-κB activation." (PMID 30184180, 2018). "PML was required for accumulation of activated STAT1 and STAT2, interacted with them and HDAC1 and HDAC2, and was associated with ISG promoters after HCMV infection." (PMID 25812002, 2015). "Thus, we propose a model by which UL23 attenuates STAT1 phosphorylation upon IFN-I stimulation upon HCMV infection." (PMID 34305856, 2021). "Taken together these data demonstrate that whilst soluble IFNβ is a potent driver of STAT-1-dependent ISG15 upregulation during HCMV infection, there is a significant component of ISG15 expression mediated by a type-I IFN signaling-independent, IRF3-dependent mechanism." (PMID 30871003, 2019). "This demonstrates firstly, that nPro/HFs are capable of upregulating ISG15 transcript and secondly that there is a soluble factor produced during HCMV infection that can induce ISG15 upregulation in a STAT1-dependent, IRF3-independent manner, most likely type I IFN." (PMID 30871003, 2019). "Further studies on these issues may elucidate the potential roles of the impact on the STAT1 signaling by these two HCMV proteins in supporting HCMV infection." (PMID 29377960, 2018). "Furthermore, after UV-HCMV infection, PML formed a protein complex with STAT1, STAT2, HDAC1, and HDAC2 and associated with ISG promoters." (PMID 25812002, 2015). "To understand if pSTAT1 was binding to either of these two sites during HCMV infection, we performed CUT&RUN paired with RT-qPCR to quantitatively detect target sequences bound by STAT1." (PMID 37289831, 2023). "Intriguingly, progressive hemophagocytosis after MMR vaccine or cytomegalovirus infections was noted in two of the previously reported cases, as well as in patients with other defects in the type I IFN pathway including STAT1, STAT2, and IFNAR2." (PMID 35091979, 2022). "In summary, our study demonstrates that UL23 disrupts STAT1 phosphorylation and suppresses IFN-I response after HCMV infection." (PMID 34305856, 2021). "In the context of HCMV infection, initiation of IFIT2 transcription was found to occur independently of STAT1 nuclear localization and in the presence of CHX." (PMID 31921100, 2019). "The common impacts on STAT1 by IE1 and UL23 via different pathways, represent an interesting and potentially important regulatory mechanism of host responses during HCMV infection." (PMID 29377960, 2018). "For instance, HCMV infection leads to the production of the tyrosine phosphatase Shp2, which inhibits IFN-γ-induced STAT1 tyrosine phosphorylation." (PMID 30075008, 2018). "Another report showed that human cytomegalovirus infection can activate the type I IFN signaling pathway, which enhances viperin transcription through the STAT1/STAT2/IRF-9 complex termed ISG factor 3 (ISGF3) by binding to the promoter response element ISRE." (PMID 27232627, 2016). "To investigate the mechanism by which PML promotes ISG transcription, we compared levels of IRF3, STAT1, STAT2, and their activated forms in control and PML-knockdown HF cells after UV-HCMV infection." (PMID 25812002, 2015).
HCMV infection (continued). "We confirmed known effects of HCMV infection on Jak1, STAT2, and IRF9 and demonstrated that, apart from STAT1, expression of the final effectors in both interferon induction and response pathways were all progressively diminished during infection." (PMID 24906157, 2014). "Given pSTAT1 binds to the viral genome at two sites upstream of UL138 during HCMV infection, we next wanted to determine if UL138 gene expression could be regulated by STAT1 signaling." (PMID 37289831, 2023). "Phosphorylation levels of IRF9, STAT1, and STAT2 were shown to decrease after HCMV infection." (PMID 34305856, 2021). "Notably, PML has been reported to mediate the recruitment of activated STAT1 and 2, along with HDAC1 and 2, onto ISG promoters (ISG54, CXCL10) during human cytomegalovirus (HCMV) infection." (PMID 29309427, 2018). "During HCMV infection, viral IE1 protein interacted with PML, STAT1, STAT2, and HDACs." (PMID 25812002, 2015). "Taken together, these data demonstrate that upregulation of this subset of ISGs by HCMV infection can occur independently of viral gene expression, in a manner that is dependent on IRF3 but not dependent on STAT1." (PMID 30871003, 2019).
diabetic nephropathy (16 papers, 2013 to 2025). "Another study has confirmed that TIMP-3 deficiency contributes to the development of diabetic nephropathy through FoxO1/STAT1 interactions." (PMID 38774282, 2024). "On the other hand, STAT1-mediated ferroptosis has been reported in recent years in different diseases such as diabetic nephropathy, radiation-induced intestinal injury, and tumors." (PMID 40103575, 2025). "FOXO1 can reduce tubulointerstitial fibrosis and tubular apoptosis in diabetic nephropathy by targeting STAT1 signaling." (PMID 34867446, 2021). "The expression of Stat1 was increased in patients with diabetic nephropathy, and the activated STAT1 was increased in high glucose-cultured mesangial cells (MCs)." (PMID 31337338, 2019). "The loss of TIMP3 can lead to diabetic kidney disease in both human and mouse via the interplay of FOXO1 and STAT1." (PMID 29796115, 2018). "Furthermore, α-SMA has been demonstrated to be a downstream protein of STAT1, and inhibition of STAT1 signaling ameliorates tubulointerstitial fibrosis in diabetic kidney disease, attenuates pulmonary vascular fibrosis, and rescues the exacerbated remodeling in myocardial infarction." (PMID 39237996, 2024). "The present study showed that AARS1 induced the lactylation of H3K18 and STAT1 to regulate ELOVL5 transcription, thus triggering ferroptosis in a diabetic nephropathy model." (PMID 40987895, 2025). "In diabetic nephropathy, HDAC4 promotes the deacetylation of signal transduction and transcriptional activator 1 (STAT1), and activated STAT1 inhibits podocyte autophagy, thereby inducing podocyte injury." (PMID 35637410, 2022). "Meanwhile, high glucose activates STAT1 and TGF β in diabetic nephropathy, and involved in the process of renal tubulointerstitial fibrosis." (PMID 31333586, 2019). "Studies on kidney biopsies from patients with diabetic nephropathy confirmed a significant reduction in TIMP3, FoxO1 and FoxO1 target genes involved in autophagy compared to controls, while STAT1 expression was strongly increased." (PMID 23401241, 2013).
acute myeloid leukemia (15 papers, 2008 to 2025). Acute myeloid leukemia (AML) is a group of neoplasms arising from precursor cells committed to the myeloid cell-line differentiation. "The hematopoietic GTPase RhoH acts as a negative regulator for IL-3-induced signals by controlling STAT activity and IL-3 Receptor α expression, ultimately resulting in the preferential activation of STAT1 and decreased cell proliferation in acute myeloid leukemia." (PMID 38702781, 2024). "Here we report a novel effect of dasatinib on inducing the differentiation of acute myeloid leukemia (AML) cells through MEK/ERK-dependent activation of signal transducer and activator of transcription 1 (STAT1)." (PMID 23825585, 2013). "It has previously been shown that Ang-1 can stimulate phosphorylation of STAT-1, STAT-3, STAT-5 and STAT-6 in human acute myeloid leukemia cells, although the physiological consequences of this were not identified." (PMID 24404127, 2014). "Finally, the inclusion of STAT1, STAT5B, and STAT3 is of relevance given the cross talk between retinoid receptors and this group of transcription factors in acute myeloid leukemias." (PMID 25888236, 2015). "Additionally, we evaluated GeneCompass by in silico deleting more transcription factors (TFs) in various cell types of different species, i.e., STAT1 on human PBMC cells, SMARCA4 on human acute myeloid leukemia cells, CBX8 on mouse embryonic stem cells, and MTA2 on mouse colonic epithelium cells." (PMID 39375485, 2024).
multiple sclerosis (15 papers, 2014 to 2025). A progressive autoimmune disorder affecting the central nervous system resulting in demyelination. "Another previous study demonstrated that GCs treatment decreases p-STAT1 expression (a key mediator of IFN-γ responsiveness) in mononuclear cells from multiple sclerosis patients." (PMID 39510764, 2024). "In another study on multiple sclerosis, IL-9 activated STAT1 and STAT5, which are known to inhibit Th17 polarization, and reduced IL-17 production." (PMID 29887863, 2018). "In conclusion, we demonstrated that GYF-21 can significantly inhibit innate and adaptive immunity via suppressing STAT1/3 and NF-κB signaling pathways, and has potential to be developed into therapeutic drug for multiple sclerosis." (PMID 28588487, 2017). "Importantly, we find upregulation of STAT1 in NSCs in a mouse model of multiple sclerosis (MS) and an increase in pathological T cells expressing IFN-γ rather than interleukin 17 (IL-17) in the cerebrospinal fluid of affected mice." (PMID 37663126, 2023). "Because STAT1 and STAT3 are required for the development of naïve T cells into Th1 and Th17 lymphocyte, pre-clinical studies examined whether simultaneous inhibition of STAT1 and STAT3 with SBT-100 would be effective therapy for multiple sclerosis." (PMID 40114923, 2025). "The transcription factor STAT1 plays a critical role in modulating the differentiation of CD4+ T cells producing IL-17 and GM-CSF, which promote the development of experimental autoimmune encephalomyelitis (EAE), an animal model of multiple sclerosis (MS)." (PMID 35587373, 2022). "STAT1, the primary transcription factor activated by IFN, has been studied as a more sensitive and reliable biomarker than other pathway-specific activated STATs and monitored in multiple sclerosis patients after IFN-β administration." (PMID 30733680, 2018).
sarcoma (15 papers, 2014 to 2025). A usually aggressive malignant neoplasm of the soft tissue or bone. "Human sarcoma cell lines (U3A, STAT1 deficient; U3A-STAT1, STAT1 complemented) were infected with TgIST-Ty expressing parasites for 16 h and then activated with IFN-γ (100 U/mL) for 1 h." (PMID 35831295, 2022). "We previously used human sarcoma (2fTGH) cells and their STAT1-deficient counterparts (U3A) to investigate mTORC1-regulated STAT1 activity and apoptosis." (PMID 31772273, 2019). "Furthermore, the IRF3/STAT1 pathway was reported to be associated with M2 polarization in a murine model of sarcoma." (PMID 35967424, 2022). "Furthermore, a study on murine sarcoma also demonstrated that tumorigenesis and progression were associated with STAT1 pathway activation." (PMID 36483553, 2022). "Moreover, knockdown of STAT1 by transfecting siRNAs into chidamide-treated sarcoma cells decreased the surface protein and mRNA expression of PD-L1." (PMID 33637599, 2021). "For example STAT3 is an oncoprotein in sarcoma, whilst STAT1 is a tumour suppressor." (PMID 26909593, 2016). "We treated the 16 sarcoma cell lines with IFN-γ, then measured the mRNA expression levels of STAT1 and PD-L1 using qRT-PCR assay." (PMID 30400799, 2018).
Crohn disease (14 papers, 2013 to 2024). A gastrointestinal disorder characterized by chronic inflammation involving all layers of the intestinal wall, noncaseating granulomas affecting the intestinal wall and regional lymph nodes, and transmural fibrosis. "Signal transduction and activator of transcription 1 (STAT1) plays a multifaceted role in the pathogenesis of Crohn’s disease, an IBD." (PMID 38420127, 2024). "Additional evidence points to increased expression of IL-22 in patients with Crohn’s disease through a Th1- mediated STAT1 and STAT3 activation, further implicating its role in innate immune activation." (PMID 35628427, 2022). "To study the impact of STAT1 on gastrointestinal inflammation with features of Crohn's disease, we deleted this transcription factor in the Caspase-8 mouse model (Casp8ΔIEC)." (PMID 34141714, 2021). "However, few chemicals have been reported for the inhibition of STAT1/ IFN-g signaling for the treatment of Crohn’s disease." (PMID 36985759, 2023). "Indeed, we show that STAT1 transcripts levels are increased in Crohn’s disease and SLE patients and they contributed to alter IL-6 responses." (PMID 33871355, 2021). "Furthermore, STAT1 alters the gene expression of Caspase-8 and Mlkl in the small intestine and interferon-induced cell death seems to plays a crucial role during Crohn's disease like ileitis." (PMID 34141714, 2021). "Additionally, in intestinal epithelial cells from patients with Crohn’s disease, IL-26 activates STAT1/3, ERK1/2, stress-activated protein kinase/JNK1/2, and Akt phosphorylation, leading to increased expression of proinflammatory cytokines." (PMID 31831038, 2019). "The details of the role of STAT1 in intestinal epithelium in the TNF model, but also in IBD and Crohn's disease, are being revealed, but await further detailed studies." (PMID 32914580, 2020).
dengue (14 papers, 2011 to 2025). "In the study of Cerny, nanostring gene expression data showed significant up‐regulation of STAT1 upon dengue viral exposure in susceptible dendritic cell populations." (PMID 30868055, 2019). "Two of the genes identified in our 5‐gene diagnostic signature are important entities in the IFN‐γ signalling cascade (STAT1 and WARS), which has been broadly implicated in the responses to enteric fever, TB, dengue and P. falciparum infection." (PMID 31468702, 2019). "By devising a unique method of collecting saliva from a large number of mosquitoes and employing inoculum size-sensitive Stat1-/- mice as a model for dengue hemorrhage, we addressed whether the mosquito vector changes DENV2 and affects its virulence in causing disease in the mammalian host." (PMID 34449772, 2021). "While several genes consistently identified dysregulated in dengue patients, such as CXCL10, ZWINT, BUB1, AURKA, STAT1, etc. there was a notable variability in gene expression patterns across the datasets." (PMID 40100920, 2025). "Dengue virus infection, in monocyte-derived dendritic cells, activates the IRF3/7/STAT1 and NF-κB anti-viral and inflammatory pathways, as well as Nrf2-dependent antioxidant genes." (PMID 27093399, 2016). "Transcription of IFN-β, STAT-1 and CCL5 was significantly up-regulated in all APC subsets upon dengue virus infection." (PMID 25474532, 2014). "For instance, STAT2 was reported to mediate STAT1-independent protection against dengue virus infection in mice that were deficient in STAT1 through the formation of non-ISGF3 complexes that involved STAT2 homodimers, and did not require STAT1." (PMID 26897526, 2016). "Despite the different conditions in vivo, with shifting cell populations and multiple interacting stimuli, 57 of these genes, including canonical ISGs such as ISG15, ISG20, OAS2, ISI27, STAT1 and STAT2, had consistently elevated transcript levels in dengue patients compared to healthy controls." (PMID 23285306, 2012). "Thus, if chikungunya virus interferes with STAT1 nuclear transport and dengue virus blocks STAT2 phosphorylation, inhibiting both STAT1 and STAT2 during chikungunya/dengue coinfection may enhance replication of both viruses." (PMID 30668574, 2019).
dermatitis (14 papers, 2016 to 2025). An inflammatory process affecting the skin. "The genes ICAM1 and STAT1 have associations with some skin disorders such as urticaria, and eczema, respectively." (PMID 39024368, 2024). "Among these, STAT1 and STAT2 are primarily activated by IFN-γ and other Th1-associated cytokines, contributing to persistent skin inflammation and tissue damage during the chronic phase of AD." (PMID 40724851, 2025). "Among the generated regulatory network, STAT1, IFITM1, ISG15, and MX1 were genes associated with the IFN signaling pathway, while STAT1 and MX1 were associated with dermatitis, and STAT1 and ISG15 were associated with the inflammatory response." (PMID 30634634, 2019). "Therefore, we evaluated the effects of SF on the phosphorylation of STAT1 in AD-like dermatitis skin lesions in NC/Nga mice." (PMID 31007602, 2019). "STAT1 and STAT2 are mainly activated in response to IFN-γ and other Th1-related cytokines and are involved in perpetuating skin inflammation and aggravating tissue damage in the chronic stage of AD." (PMID 39769302, 2024).